IL6 (interleukin 6)
Diseases named in the same sentence as IL6 in open-access papers (continued):
Sharing a sentence is not in itself a finding about the gene and the disease.
infection (continued). "During infection, proinflammatory cytokines such as IL-6 promote transcriptional induction of hepcidin via signal transducer and activator of transcription (STAT) signaling." (PMID 32210768, 2020). "The raised levels of IL-6 (632 ± 526Vs 17 ± 8 pg/ml, day 15 post-infection) and IL-10 (88 ± 60 vs. 30 ± 27.41 pg/ml, day 12 post-infection) were quantified in the mice infected with C9-M parasites and compared with NF54 wild type P. falciparum." (PMID 33013831, 2020). "The mRNA expression level of both IL-2 and IL-6 was notably increased after 1 and 2 h of infection and was further dramatically enhanced after 6 h of infection (p < 0.01)." (PMID 30736473, 2019). "The authors also demonstrated that treating mice with GalXM prior to infection induced immune protection and this phenomenon was dependent on IL-6 and IL-17 production." (PMID 31275938, 2019). "Given the potential role of IL-6 in human VHFs, our model offers an opportunity to explore the potential of therapies, such as neutralizing antibodies, aimed at modulating IL-6 responses during infection." (PMID 30650570, 2019). "The adequate production of proinflammatory cytokines such as INF-γ, TNF-α, IL-1, IL-12, and IL-6 is essential for the control of infection by intracellular parasites." (PMID 31827186, 2019). "Bedside detection of raised IL-6 levels in the blood would aid the diagnosis of infection, thereby enabling the fast and effective treatment necessary to combat this disease." (PMID 31802241, 2019). "Infection of pigs with this mutant CSFV was characterized by the sustained accumulation of IL-6 in tonsils." (PMID 31134045, 2019). "IL-6 is considered a proinflammatory cytokine that has typically pro-tumorigenic effects during infection." (PMID 31121000, 2019). "This included involvement of many inflammatory pathways including IL-8 and IL-6 signaling and the Th1 pathway, suggesting a robust immune response to infection by both APEC strains." (PMID 31998322, 2019). "Inflammation or infection of the placenta induces a robust signaling response, including increased concentrations of IL-1β, IL-6, IL-8 and TNF." (PMID 31537532, 2019). "The expression of IL-6 in the infection groups was higher than that in the control groups in the liver, proventriculus, small intestine, thymus, kidney, and bursa of Fabricius and significantly higher than that in the control group in the cecum." (PMID 31694169, 2019). "IL6 was induced between 13 and 20 fold by PGC1β 24 and 48 h from infection and decreased by PGC1α but only 72 h from infection." (PMID 31614775, 2019). "Pro-inflammatory cytokines (including IL-1β, IL-6, and IL-8) are necessary to initiate the inflammatory response during infection." (PMID 31616382, 2019). "Chronic inflammation often occurs due to either unresolved injuries or pathogenic infections that cause over-production of multiple pro-inflammatory cytokines such as TNF, IL1, IL6, IL17, HMGB1 and other mediators such as nitric oxide." (PMID 30947238, 2019). "Interleukin-6 is well known as a pro-inflammatory cytokine, playing an important role in acute inflammatory responses triggered by infection and tissue damage." (PMID 30615687, 2019). "Taken together, we conclude that PRV footpad infection induces high G-CSF and IL-6 concentrations in many tissues very early after infection." (PMID 31675371, 2019). "CRP synthesis is induced in the liver by proinflammatory cytokines – especially interleukin 6 (IL-6) – in response to infection, inflammation and tissue damage." (PMID 29764522, 2019). "The impact of PSMs on the cytokine profile in the blood plasma was less prominent, only showing increased IL-6 production upon infection with the S. aureus USA300 WT strain." (PMID 31134074, 2019). "This supports the idea that the pro-inflammatory cytokine IL-6 is produced early after infection as part of the induced innate immune response and has been associated with the recruitment of inflammatory cells and severe pathology." (PMID 31675983, 2019).
infection (continued). "Interleukin-6 (IL-6), a multifaceted cytokine that mediates responses to injury or infection, is also involved in immune diseases and cancers." (PMID 30927911, 2019). "Dam 2 had an increase in IL-1β, IL-2, IL-6, IL-7, IL-12, IL-15, IL-16 and IL-17A, peaking on day 14 post-infection for all but IL-12 and IL-15 which peaked on day 7 post-infection." (PMID 30657788, 2019). "Similar with findings regarding that IL-6 blockade protects mice from EV71-induced immunopathogenesis in the intraperitoneal infection model." (PMID 31730654, 2019). "For each strain, the quantity of IL-6 and IL-8 secreted by epithelial cells during infection was determined." (PMID 30992458, 2019). "Our results found the accuracy of serological tests, including ESR, CRP and IL-6, was poor in predicting persisting infection before second-stage prostheses implantation, which was similar with previous studies on the two-stage exchange arthroplasty of PJI." (PMID 31159792, 2019). "CRP is an acute phase reactant produced by hepatocyte-derived IL-6-dependent biosynthesis in inflammatory conditions, particularly in response to infection." (PMID 31781117, 2019). "This conclusion is supported by our data showing marginal increments in serum levels of GM-CSF and IL-6 under infection by E. muris." (PMID 31575880, 2019). "We further investigated soluble proinflammatory cytokines in plasma and lung homogenates (IL-1β, KC/GRO, TNFα, IL-6, IL-12p70, and IFNγ) as well as pulmonary influx of myeloid-derived cells 2 weeks into COXi treatment (week 6 of infection)." (PMID 31396568, 2019). "In most patients with grade 4–5 infection, a second IL-6 peak induced by grade 4–5 infection appeared immediately after the abrogation of the first CRS-related IL-6 peak." (PMID 31640816, 2019). "IL-6 is considered the most important inducer of hepatocyte synthesis of acute-phase proteins in response to infection/inflammation stimuli, and CRP is produced mainly in the liver in response to IL-6." (PMID 31394828, 2019). "Cytokines that are upregulated during acute human infection include IL-6, IL-16, IL-17, IP-10, MCP-1, MIF, stromal cell-derived factor-1α, IL-1rα, IL-2rα, G-CSF, GM-CSF, VEGF, IL-7, IL-12p40, and IFN-α2." (PMID 31053842, 2019). "At 24 h, 48 h, and 72 h post-infection, significantly lower levels of IL-1Ra, IL-6, IL-8, IL-10, IL-12p40, TNF-α, MCP-1, and MIP-1b were detected in ESRD group." (PMID 31875015, 2019). "Based on the dynamic changes of interleukin (IL)-6 and ferritin, we proposed the “double peaks of IL-6” pattern as a feature of life-threatening infection during the first 30 days after CTI." (PMID 31640816, 2019). "At the late phase of infection (72 h post-infection), levels of IL-1Ra, IL-6, IL-8, IL-10, IL-12p40, GM-CSF, TNF-α, MCP-1, and MIP-1b still remained significantly low for ESRD group, as compared to control group." (PMID 31875015, 2019). "Interleukin 6 (IL-6), a pro-inflammatory cytokine, plays an important role of regulating the acute phase response during inflammation and infection." (PMID 30813467, 2019). "The rise of IL-10 and IL-6 in the PMN-depleted infected mice at later times of infection correlated with the decreasing levels of IFN-γ." (PMID 30804100, 2019). "TNF-α is detectable early in the amniotic fluid following bacterial colonisation and stimulates the production of IL-6, IL-8, matrix metalloproteinases and PGE2 during infection-associated PTL." (PMID 31513646, 2019). "We observed that the infection induced upregulation in the mRNA expression of liver IL-1β, IL-6, IFN-γ, and TNF-α, while treatment of P. chabaudi-infected mice with IE resulted in a significant downregulation in the expression levels of these cytokines." (PMID 30838089, 2019). "With respect to the other parameters, only IL-6 differed significantly (p = 0.0029) between neonates that developed infections and their matched controls." (PMID 31993410, 2019).
infection (continued). "SBCMV infection of this IBRB Tricell mixture for 96 h resulted in increased levels of IL-6, MMP9, and stem cell factor with a concomitant decrease in granulocyte-macrophage colony-stimulating factor and TNF-α." (PMID 30909422, 2019). "While IL-3 and IL-9 were decreased in both infection groups, IL-6 was only significantly decreased in T. canis-infected and GM-CSF only in T. cati-infected mice." (PMID 31315623, 2019). "In another study, it was demonstrated that, after infection by Trypanosoma cruzi, IL-6 boosted the recruitment of monocytes and determined the profile of M2 cardiac macrophages during infection." (PMID 31235718, 2019). "An increase in the proinflammatory cytokine IL-6 occurred during the acute infection phase with T. cruzi for both the wild-type and knockout mice." (PMID 31772504, 2019). "Other studies have reported that IL-6 production is typically involved in the host defence observed in the infection or wounded tissues during the acute-phase response." (PMID 31873180, 2019). "Assessment of the PLF total cell counts and the release of cytokines KC and IL-6 revealed a significant increase in the total cells within the peritoneal cavity upon infection." (PMID 30988402, 2019). "Following infection, cytokines, such as IL-1β, IL-6, TNF-α, and inducible nitric oxide synthetase (i-NOS), that coordinate immune/inflammatory responses are triggered and activated." (PMID 30814582, 2019). "Infection of primary human umbilical cord vein endothelial cells (HUVECs) with A. baumannii led to the secretion of interleukin (IL)-6 and IL-8 in a time- and Ata-dependent manner." (PMID 31874074, 2019). "TNF-α and IL-6 are the two major inflammatory cytokines, and they are promptly and transiently produced in response to infection and tissue injury." (PMID 31671698, 2019). "IL-6 is considered one of the most important cytokines during an infection, along with interleukin 1 (IL-1) and tumor necrosis factor alpha (TNF-a; Dienz and Rincon, 2009)." (PMID 31134045, 2019). "Infection of epithelial cells with E. coli (MS499) significantly increased the secretion of IL-6 in primary epithelial cell cultures." (PMID 30923927, 2019). "Participants in the top third of IL-6 levels at baseline were more likely to be female, have higher BMI and have a self-reported infection around the time of blood collection at age 9 years." (PMID 30414442, 2019). "Significant effects (p < 0.01) due to infection status were present for G-CSF, IL-6, IP-10, KC, MCP-1, and MIG for both ALOX8+/+ and ALOX8−/− mice." (PMID 31013822, 2019). "In PUUV infection, on the other hand, IL-6 has predicted the outcome, but the predictive value of CRP is less clear." (PMID 31438470, 2019). "Infection of epithelial cells, which are the primary targets of Chlamydia, results in production of cytokines and chemokines such as IL-8, IL-6, and GM-CSF that recruit inflammatory leukocytes to the site of infection." (PMID 32039039, 2019). "It has been described that hRSV-infected BALB/c mice can exhibit increased levels of IL-6 in BALFs at 12 h post-infection that remains elevated up until 14 days post-infection." (PMID 30936869, 2019). "As we known, hs-CRP is a reactant involved in the acute-phase response and rapidly increases in the presence of infection or inflammation, which is stimulated by the release of proinflammatory cytokines, including IL-1, IL-6 and TNF-α." (PMID 31296192, 2019). "IL-8 levels peaked after 8 h (WT: 2.3 ± 0.002 ng/mL and 1.2 ± 0.02 ng/mL for Δata) and decreased over time, whereas IL-6 continuously increased over time up to late infection stages at 14 h (WT: 1.2 ± 0.1 ng/mL; Δata: 0.14 ± 0.02 ng/mL)." (PMID 31874074, 2019). "After Trichinella infection, VL group showed a significant increase in TNF-α, IL-1, and IL-6 levels in the serum (P < 0.05), and these results indicate that activated immune cells continue to release inflammatory cytokines after an infection." (PMID 31366385, 2019).
infection (continued). "Significantly increased concentrations of PCT, IL-6, and sCD163 were observed in the limited infections compared with controls." (PMID 31915467, 2019). "For instance, IL-6 secreted by the local infected cells recruits neutrophils at the early stage of infection, and then IL-6 secreted by neutrophils attracts macrophages and monocytes to the inflamed sites 24 h after the initial infection." (PMID 31474976, 2019). "Serum C-reactive protein (CRP) is an acute phase protein induced mainly by IL-6 in response to inflammatory conditions, particularly infection." (PMID 31781117, 2019). "IAV infection increased the mRNA expression at day 3 post-infection (105 PFUs) of IL-6, CCL3, CXCL2, and G-CSF, IL-1β and TNF-α (p < 0.05)." (PMID 30787331, 2019). "Both infection groups showed a continuous decrease of pro-inflammatory cytokine concentrations, including TNF-α, IFN-γ, GM-CSF and IL-6, in the cerebrum over the course of infection." (PMID 31315623, 2019). "Compared to group 2, the level of IL-6 in group 1 was significantly lower at most post infection days." (PMID 31387285, 2019). "Such a release profile will likely have significant advantages during longer-term infection, whereby the sustained presence of antibiotic will reduce IL-6 production and reduce bacterial load more effectively than the free drug." (PMID 30923927, 2019). "In line with an increased infection rate, smoking reduced 25OH vitamin D3 (immune-modulatory), IL-1β, IL-6, TNF-α, and IFN-γ serum levels." (PMID 30909629, 2019). "IL-6 mediate the initial innate immune system response to injury or infection and its plasma concentration increases and falls rapidly." (PMID 31261907, 2019). "In order to further study viral activation of innate immune pathways potentially dependent on Ncbp3, we quantified amounts of secreted IRF- and NF-κB-regulated cytokines IP-10 and IL-6 upon infection of MEFs with IAV-ΔNS1." (PMID 31856218, 2019). "To determine the tissue response to infection with N. gonorrhoeae, we have measured the amount of pro-inflamatory cytokines IL-6 and TNFα, and chemokine IL-8 released into the apical medium 24 h post infection." (PMID 31417529, 2019). "In particular, the production of IL-1β and IL-6 was reduced in the groups treated with UA compared with the infection group, and the expression of IL-10 and IL-12 was significantly increased in T. gondii-infected cells treated with UA." (PMID 31075881, 2019). "The level of the pro-inflammatory cytokines TNF-α, IL-1β and IL-6 and the anti-inflammatory cytokine IL-10 was quantified at 10 h post-infection in the supernatants of infected MDM." (PMID 31694333, 2019). "IL-6 levels, BMI, self-reported infection and British White ethnicity were similar between the analytic and missing samples." (PMID 30414442, 2019). "Among these cytokines, IL-6 is secreted by macrophage to stimulate the immune response, e.g., fatigue and infection." (PMID 32082125, 2019). "IL-6 has been nominated as a biomarker in older patients that discriminates ASB from symptomatic infection." (PMID 31338112, 2019). "S. Typhimurium induced the expression of IL-6, IL-8, IL-1β, TNFα and IL-10 genes in CaCo-2 cells after 8-h infection." (PMID 31490973, 2019). "High levels of inflammatory cytokines including IL-6 and IFN-γ gamma were shown to be induced by infection with highly pathogenic influenza viruses and high lung viral titers, causing severe inflammatory lung disease." (PMID 31246961, 2019). "Similar to the macrophages, infection with the sipA sopB sopE2 sopE mutant led to Il6 expression, most likely induced by TLR activation." (PMID 31109951, 2019). "This upregulation was observed during infection with a highly virulent VSV strain, suggesting a potential association between IL-6 levels and virus virulence in pigs." (PMID 31134045, 2019).
infection (continued). "It is well known that many viruses are capable of modulating the expression of inflammatory cytokines (e.g., IL-6), thus allowing the virus to establish a successful infection." (PMID 31601264, 2019). "Cytokines IL-6 and IL-17A, in particular, are important for coordinating neutrophil trafficking to areas of infection." (PMID 31206562, 2019). "In contrast, the level of IL-10 and IL-6 in αIFNAR1 treated mice was decreased as compared to Isotype mice at day 21 post-infection." (PMID 31801478, 2019). "In the late phases between 5 and 7 days post-infection, the inhibition of cytokines, except for IL-6 and CCL-5, was minor." (PMID 31293574, 2019). "KC recruits neutrophils to the infected lung while IL-6 is usually involved in the acute phase responses toward infections." (PMID 31013822, 2019). "It remains to be seen if the relative difference in inhibition of γc cytokine receptors vs other cytokine receptors (eg, IFN and IL‐6) with tofacitinib, compared with JAK inhibitors that spare JAK3, translates into a meaningful difference in infection risk." (PMID 31832202, 2019). "When accompanied by infection or inflammation, IL-6, and TGF-β initiate the differentiation of the initial CD4+ T cells into Th17 cells, thereby inducing chronic inflammatory response dominated by Th17 cells." (PMID 31757053, 2019). "The kinetics of IL-6 production reflecting its roles in the early response to infection such as leukocyte recruitment, B lymphocyte development, antibody secretion by plasma cells and the regulation of acute-phase proteins." (PMID 30923927, 2019). "For example, high levels of IL-6 have been correlated with CMV reactivation and poor prognosis for transplant patients; perhaps this is because ISGs produced by IE1 re-routing the IL-6 response to enhance infection." (PMID 31921100, 2019). "In contrast, PCLS from HDM-sensitized mice showed an attenuated antiviral response, but exaggerated IL-4, IL-6, and IL-10 secretion upon infection." (PMID 31640701, 2019). "Such pathways are activated either by mono- or polymicrobial infections, resulting in an increase in the expression of proinflammatory molecules such as IL-6, IL-8, IL-1β, and TNF-α." (PMID 31049022, 2019). "After high-dose infection (5 × 106 CFU per mouse), bronchoalveolar lavage fluid (BALF) TNF levels recovered at 2 h and IL-1β and IL-6 at 4 h were higher in response to the TIGR4 strain compared to infection with the TIGR4 Δcps strain." (PMID 31551336, 2019). "DHA pre-treatment was capable of reducing this secretion at 48 and 72 hours for MCP-1 and at 96 hours of infection for IL-6, where this cytokine had its apex of secretion compared to other times." (PMID 31882804, 2019). "A number of genes involved in resistance to infection such as il17, il22, and il6 were also increased." (PMID 30867416, 2019). "Deficiency of IL-10 improved the anti-virus ability of the mice at the early phase of infection through increasing either pro-inflammatory cytokines’ (IL-2, IL-6, IL-12, TNF-α, IFN-α, IFN-γ) production or PCV2-specific antibodies." (PMID 31551984, 2019). "In healthy humans, the normal physiological concentrations of IL6 in serum are low; therefore, elevated IL6 concentrations in the serum indicate systemic inflammation or infection." (PMID 30841512, 2019). "In support of this theory, serum levels of IL-6 are increased in Dectin-1 KO mice during infection with C. albicans, and cells from these mice demonstrate the highest Candida-induced IL-17 response." (PMID 31447813, 2019). "The induction of TNF-α, IL-6, and IL-1β was maintained at relatively low levels compared with infection with L. monocytogenes or treatment with LPS." (PMID 31877174, 2019). "BeAn-infected SJL mice express several genes involved in the innate immune responses (Tlr7, Tlr8, Tlr9, Myd88, Isg15, Isg20, Mx1, and IL6) in the spinal cord during the late phase of TMEV-IDD at 165 days post infection." (PMID 30669615, 2019).